TMEM184C (transmembrane protein 184C)
Description:
Possible tumor suppressor which may play a role in cell growth.
Synonyms: TMEM34; FLJ10846; SLC51C3
Tractability: Antibody: UniProt predicts a signal peptide or a membrane-spanning region. PROTAC: ubiquitination databases record sites on it; its protein half-life has been measured.
Gene: Protein-coding gene on chromosome 4 (147,617,386 to 147,672,044, forward strand). Ensembl gene ENSG00000164168.
Subcellular location: Membrane
Subcellular location (Human Protein Atlas): Vesicles; Nucleoplasm
Gene Ontology:
Molecular function: transmembrane transporter activity
Biological process: transmembrane transport
Cellular component: membrane
Genetic constraint (gnomAD): Loss-of-function variants: 20 observed, 48.91 expected, observed/expected ratio (o/e) 0.41, 90% interval 0.29 to 0.59. The synonymous counts are far from expectation, so gnomAD's model fits this gene poorly and the ratio says little. Missense variants: 310 observed, 500.85 expected, observed/expected ratio (o/e) 0.62, 90% interval 0.56 to 0.68. Synonymous variants: 137 observed, 177.19 expected, observed/expected ratio (o/e) 0.77, 90% interval 0.67 to 0.89.
Homologues: Orthologues: chimpanzee TMEM184C (100% identical), macaque TMEM184C (99% identical), rabbit TMEM184C (96% identical), pig TMEM184C (95% identical), dog TMEM184C (95% identical), guinea pig TMEM184C (93% identical), mouse Tmem184c (79% identical), tropical clawed frog tmem184c (77% identical), zebrafish tmem184c (75% identical), rat Tmem184c (71% identical), Drosophila melanogaster CG5850 (42% identical). Paralogues in human: TMEM184B (30% identical), TMEM184A (29% identical), SLC51A (12% identical).
Diseases named in the same sentence as TMEM184C in open-access papers:
TMEM184C is named in the same sentence as 4 diseases in open-access papers, as found by Europe PMC text mining. Sharing a sentence is not in itself a finding about the gene and the disease. The quoted sentences say what the papers report.
cerebral aneurysm (1 paper, 2021). "In the present analysis, TMEM184C and PRMT10 showed significant association with cerebral aneurysm." (PMID 34616426, 2021).
TMEM184C also shares sentences with these, for which no sentence is quoted: anaplastic thyroid cancer (2 papers); cancer (1); tumor (1).